GAGE1 (G antigen 1)
Description:
Antigen, recognized on melanoma by autologous cytolytic T-lymphocytes.
Synonyms: GAGE-1; CT4.1
Tractability: Antibody: the Human Protein Atlas places it where antibodies can reach.
Gene: Protein-coding gene on chromosome X (49,599,020 to 49,608,538, forward strand). Ensembl gene ENSG00000205777.
Subcellular location (Human Protein Atlas): Plasma membrane; Cytosol; Golgi apparatus
Homologues: Orthologues: chimpanzee GAGE10 (84% identical). Paralogues in human: GAGE12F (98% identical), GAGE12G (98% identical), GAGE12J (98% identical), GAGE13 (98% identical), GAGE12C (97% identical), GAGE12D (97% identical), GAGE12E (97% identical), GAGE12H (97% identical), GAGE2A (95% identical), GAGE2E (93% identical), GAGE10 (91% identical), PAGE1 (54% identical), and 10 more.
Diseases named in the same sentence as GAGE1 in open-access papers:
GAGE1 is named in the same sentence as 23 diseases in open-access papers, as found by Europe PMC text mining. Sharing a sentence is not in itself a finding about the gene and the disease. The quoted sentences say what the papers report.
melanoma (5 papers, 2006 to 2018). A malignant, usually aggressive tumor composed of atypical, neoplastic melanocytes. "For example, GAGE expression in malignant melanomas was observed in 17% of specimens in our study, while a previous study showed that 30% of malignant melanomas were GAGE-1-8 mRNA-positive." (PMID 16773077, 2006). "GAGE-1 was the first gene of the GAGE family to be identified from the melanoma cell line MZ2-Mel." (PMID 23625514, 2013). "The immunomodulatory activity of different DHAs on additional CTAs expression (i.e., MAGE-A2, -A4, -A10, GAGE1-2, SSX1-2, and SSX1-5) was investigated also by RT-PCR analysis in 14 melanoma and 10 hematological cancer cell lines treated with 1 μM guadecitabine, DAC or AZA." (PMID 30581389, 2018).
ovarian carcinoma (2 papers, 2010 to 2024). A malignant neoplasm originating from the surface ovarian epithelium. "In ovarian cancer tissues, MAGE-1 and MAGE-3 were highly expressed with expression rates of 53.7% (22/41) and 36.6% (15/41), while GAGE-1/2 and BAGE had relatively low expression rates of 26.8% (11/41) and 14.6% (6/41)." (PMID 20423514, 2010). "In ovarian cancer tissues, MAGE-1 and MAGE-3 was highly expressed, with expression rates of 53.7% (22/41) and 36.6% (15/41), while GAGE-1/2 and BAGE had relatively low expression, with rates of 26.8% (11/41) and 14.6% (6/41)." (PMID 20423514, 2010). "Although the expression of GAGE-1/2 and BAGE was low in ovarian cancer tissues, their positive expression rates were relatively high in serous cystadenocarcinomas." (PMID 20423514, 2010). "In the present work, the mRNA expression of MAGE-1, MAGE-3, GAGE-1/2 and BAGE was analyzed by reverse transcription polymerase chain reaction (RT-PCR), and the feasibility of their gene products as ovarian cancer markers and immunotherapy targets was also evaluated." (PMID 20423514, 2010).
acute myeloid leukemia (1 paper, 2016). Acute myeloid leukemia (AML) is a group of neoplasms arising from precursor cells committed to the myeloid cell-line differentiation. "For instance, promoter methylation of GAGE1 has been reported in PCa cell lines, while ROPN1 has been found to be expressed in a subset of acute myeloid leukemia (AML) patients." (PMID 26885621, 2016).
kidney chromophobe (1 paper, 2023). "At the same time, GAGE1 showed a similar effect in five cancer types, including kidney chromophobe, kidney renal papillary cell carcinoma, liver hepatocellular carcinoma, lung squamous cell carcinoma, and prostate adenocarcinoma." (PMID 38117798, 2023).
liver neoplasm (1 paper, 1999). Tumors or cancers of the LIVER. "Therefore, the RT-PCR assays for GAGE-1, -2 and MDM2 might be useful adjuncts in cytodiagnosis of liver neoplasms." (PMID 10389981, 1999).
multiple myeloma (1 paper, 2013). "This analysis revealed significant down-regulation by CYCLON knockdown of a proliferation gene expression signature that includes cancer testis antigens (e.g. MAGEA1, MAGEA3, MAGEA6, GAGE1), and that characterizes an aggressive subtype of multiple myeloma." (PMID 23828858, 2013).
non-small cell lung carcinoma (1 paper, 2019). A group of at least three distinct histological types of lung cancer, including non-small cell squamous cell carcinoma, adenocarcinoma, and large cell carcinoma. "The oncogenic effect of circ_0016760 is attributed to the sponging activity of miR-1287 and the increased expression of cancer/testis antigen family 4 member 1 (GAGE1) in non-small cell lung cancer human cell lines A549 and H1299." (PMID 31080413, 2019).
ovarian tumor (1 paper, 2023). "For ovarian tumor samples, we detected six hub genes: GAGE2A, GAGE1, MAGEA9, CTAG1A, CTAG1B, and MAGEA1." (PMID 37835834, 2023).
cancer (10 papers, 2013 to 2023). A tumor composed of atypical neoplastic, often pleomorphic cells that invade other tissues. "One network comprises well known cancer antigens (e.g. GAGE1, MAGEB2, MAGEC2 and SSX1) associated with short overall survival and additional aggressive tumour properties." (PMID 36649303, 2023). "We first compared gene expression between recurrent and nonrecurrent cases, and we found that recurrence was associated with higher expression of cancer/testis antigen (CTA) genes including MAGEA12, GAGE1, and GAGE2C as well as with lower expression of GZMK." (PMID 37402831, 2023). "SSX2 and GAGE1 genes were expressed in different types of cancer cells." (PMID 27454254, 2016). "Therefore, SSX2, UBL4B and GAGE1 were further validated in 33 human cancer cell lines and tissues." (PMID 27454254, 2016). "Notable exclusions include the cancer/testis antigens MAGEA1, MAGEA3, MAGEA6, GAGE1, GAGE2, GAGE4 and GAGE5, which were originally identified as being strongly upregulated in the PR subgroup but are not upregulated in our PTTG1 high patients." (PMID 26445238, 2015).
tumor (6 papers, 2011 to 2023). "The examination indicated the hub genes in tumor samples, including GAGE2A, GAGE1, MAGEA9, CTAG1A, CTAG1B, and MAGEA1; and the hub genes in healthy ovarian tissue samples, including SPA17, MAGEC1, KDM5B, SSX4, and MAGEA9." (PMID 37835834, 2023). "Pyk2, MDR1, GAGE1, MAP7 and STAT1 were found to be overexpressed in more than 60% of the tumor liver tissues compared to the adjacent non-tumor liver tissues (*p<0.05)." (PMID 22096562, 2011).
GAGE1 also shares sentences with these, for which no sentence is quoted: astrocytic tumor (1 paper); blood cancers (1); brain tumors (1); glioma (1); hematological cancer (1); hepatocellular carcinoma (1); hyperplasia (1); liver cancer (1); lung squamous cell carcinoma (1); lymph node metastasis (1); ovarian benign tumor (1); prostate adenocarcinoma (1); serous cystadenocarcinoma (1).